HHIP (hedgehog interacting protein)
Diseases named in the same sentence as HHIP in open-access papers (continued):
Sharing a sentence is not in itself a finding about the gene and the disease.
tumor (continued). "Thus, it is intriguing to speculate that restoring IGFBP3 expression and/or use of demethylating drugs could contribute to new therapeutic strategies for HB, especially with the existence of additional epigenetically silenced genes in this tumor type, such as HHIP, RASSF1, SOCS1, APC and CASP8." (PMID 22401581, 2012). "In this study, we bioinformatically analyzed a panel of 12 candidate TSGs (BCO2, CDKN2A, CPS1, HHIP, miR-122-5p, MT1E, MT1M, PSAT1, PTGR1, PZP, TMEM106A, and TTC36) that are epigenetically silenced and under-expressed in HCC tumor samples compared to normal tissue." (PMID 37120619, 2023). "HHIP is also an anti‐tumour gene and a negative feedback factor in the HH pathway that directly inhibits HH." (PMID 32525231, 2020). "Likewise, the results showed that most LAC cell lines (except for A549) showed a significantly reduced HHIP, but comparable GLI1 and SHH mRNA levels as compared to non-tumor lung epithelial cells BEAS-2B or NL20." (PMID 27015549, 2016). "Cells from CLH21, a relapsed LAC tumor harboring EGFR-T790M mutation, were not sensitive to Cyclopamine or HHIP overexpression, presumably due to the T790M-driven EGFR activation that maintained cell survival." (PMID 27015549, 2016). "In vitro analysis showed that most LAC cell lines did not express significantly enhanced SHH or GLI1 than non-tumor lung epithelial cells, but had a remarkably reduced HHIP expression." (PMID 27015549, 2016). "Cells overexpressing HHIP did not form tumor in 2 of the 8 implanted mice, while control cells formed tumors in all mice." (PMID 27015549, 2016). "To verify whether HHIP influences in vivo tumor formation and the growth of LAC cells, we implanted LAC cells overexpressing HHIP or RFP subcutaneously in nude mice." (PMID 27015549, 2016). "Nevertheless, how HHIP may regulate HH pathway and tumor progression has not been well studied in NSCLC." (PMID 27015549, 2016). "More specifically, tumor-promoting target genes, e.g. MMP7/9, IL-8 and VEGFA, were synergistically upregulated, while intriguingly negative modulators of HH/GLI signaling, such as HHIP and PTCH1, were downregulated." (PMID 23762360, 2013).
cancer (24 papers, 2014 to 2024). A tumor composed of atypical neoplastic, often pleomorphic cells that invade other tissues. "For the one driver gene, it was HHIP, a hedgehog-interacting protein associated with cancer stemness." (PMID 38666214, 2024). "Decreased HHIP expression has been identified in many types of cancer and is associated with hyperactivation of HH signaling pathway which directly promotes cancer progression." (PMID 33415068, 2020). "To pursue possible roles of HHIP in carcinostasis, we first analyzed HHIP expression in 33 types of human cancers." (PMID 37568084, 2023). "Consistently, HHIP staining showed that the myofibroblasts were sparsely distributed and located close to cancer cells." (PMID 36463319, 2022). "For example, MAPK8IP2, ADAMTS12, and CHAF1B were upregulated in over five cancer types, while HHIP, PROX1, and PLCG2 were downregulated in over five cancer types." (PMID 35654793, 2022). "Data from another group supported the tumor cell-intrinsic activation of Hh signaling: when enriching for CD133+ as a marker for cancer stem cells, this study reported increased GLI1 and HHIP expression in CRC cancer stem cells compared to normal mucosa." (PMID 33498528, 2021). "HHIP was chosen as a candidate gene because it has a potential miR-199b-5p binding site in its 3’UTR, and study have found that HHIP plays an anti-cancer role in GC." (PMID 34532291, 2021). "In the study of Hedgehog signaling pathway and the expression of various molecules in malignant tumors, the expression of HHIP gradually attracted the attention of researchers." (PMID 31765425, 2019). "Independent samples t test was performed for GSE43458 data, finding that the expression of HHIP mRNA of cancer patients (2.865±0.158) was significantly lower than that of normal people (3.285±0.152)." (PMID 31765425, 2019). "Many studies have found that the expression of HHIP in malignant tumors is lower than that in normal tissues." (PMID 31765425, 2019). "Several recent studies reported that HHIP is hypermethylated and transcriptionally down-regulated in some cancers and mouse models." (PMID 30241415, 2018). "Among the top 40 regulated genes, we also found increased expression of hedgehog-interacting protein (HHIP), which plays important roles in promoting cancer cell growth in the stromal compartment." (PMID 29662633, 2018). "It has been reported that HHIP was epigenetically silenced by promoter hypermethylation in different types of cancer." (PMID 27015549, 2016). "In this study, we performed expression analysis for HHIP in multiple types of human cancer." (PMID 37568084, 2023). "In this study, we first performed pan-cancer analysis for HHIP’s expression via The Cancer Genome Atlas (TCGA) and The Genotype-Tissue Expression (GTEx) data and found that HHIP might be a potential anti-oncogene for CRC." (PMID 37568084, 2023). "The role of HHIP in cancer has been reported in many studies." (PMID 37568084, 2023). "Results showed that the expression levels of OLR1 and HHIP genes in NSCLC were much higher than in other cancer types, indicating that these two genes could serve as specific biomarkers in NSCLC progression." (PMID 36011391, 2022). "The results suggest that HHIP+ myofibroblasts might adapt and respond to regulate cancer cell proliferation and to modulate immune reactions in cancer tissues." (PMID 36463319, 2022). "However, the role of HHIP in cancer is poorly understood, although it is well known that inactivating mutations in PTCH1 or Suppressor of fused homolog (SUFU) or activating mutations in SMO contribute to tumorigenesis through HH signaling activation." (PMID 30241415, 2018). "However, gene activation in cancer-related HHIP+ myofibroblasts was highly altered." (PMID 36463319, 2022). "HHIP may provide a broader clinical perspective to elucidate the occurrence and development of malignant tumors, and the early diagnosis, treatment, and prognosis judgment of malignant tumors." (PMID 31765425, 2019).
cancer (continued). "When comparing RM with PC, we identified key regeneration-related genes APOD and IBSP, along with several significant pathways: cAMP signaling pathway (HHIP), cytokine-cytokine receptor interaction (IL17D), pathways in cancer (HHIP, DAPK2), and biosynthesis of cofactors (RDH12, HAAO)." (PMID 39684926, 2024). "In addition, three common signature genes in the pathways concerning cancer were endothelin receptor B (EDNRB), hedgehog-interacting protein (HHIP), and MMP1." (PMID 33046043, 2020).
infection (4 papers, 2011 to 2023). The state of being infected such as from the introduction of a foreign agent such as serum, vaccine, antigenic substance or organism. "The regulatory networks miRNs–mRNA showed that FRS2 and AP1S2 target genes interacted with gga-miR-204 and gga-miR-1729-5p, while HHIP target gene is regulated by two miRNAs, gga-miR-19b-3p and gga-miR-132a-3p, at 7 days post-infection." (PMID 38288128, 2023). "After infection with LV-HHIP or LV-CON for 72 h, the HHIP promoter methylation levels in AGS cells were detected by both MSP and BSP analysis." (PMID 33415068, 2020).
gastrointestinal tumors (2 papers, 2014 to 2020). "HHIP is located on chromosome 3q31.21-31.3 and HHIP loss could lead to gastrointestinal tumors." (PMID 33415068, 2020). "The hypomethylation of HHIP, the inhibitor of SHH, has been observed in gastrointestinal tumors." (PMID 25013484, 2014).
metabolic disorders (1 paper, 2023). "Further, we found that serum HHIP levels were elevated in individuals with IR and PCOS, and these findings indicate that HHIP may be a biomarker of metabolic disorders and a potential predictor of PCOS." (PMID 36769536, 2023).
musculoskeletal disorders (1 paper, 2021). "Similarly, SOX-9 and HHIP loci were found to be associated with DXA-measured bone area.The genetic associations with hip shape in adolescents reported here may be relevant for future risk of age-related musculoskeletal disorders." (PMID 33285254, 2021).
renal disease (1 paper, 2022). "A study of renal disease showed that the expression of hedgehog‐interacting protein (HHIP) was significantly elevated in the kidney of diabetic mice, enhancement of HHIP promoted endothelial EndMT and apoptosis, while knockdown of HHIP significantly ameliorated renal injury." (PMID 35560773, 2022).
HHIP also shares sentences with these, for which no sentence is quoted: chronic bronchitis (2 papers); lung adenocarcinoma (2); lymph node metastasis (2); non-small cell lung carcinoma (2); pulmonary hypertension (2); Type 2 Diabetes (2); Alzheimer disease (1); chordoma (1); chronic hepatitis B (1); esophageal cancer (1); fibroma (1); Hip dysplasia (1); ischemia (1); joint diseases (1); lipid metabolism disorders (1); myeloid leukemia (1); oral squamous cell carcinomas (1); osteoarthritis (1); ovarian carcinoma (1); Papillary Thyroid Cancer (1); prediabetes (1); prostate carcinoma (1); sex cord-stromal tumor (1); squamous cell lung carcinoma (1).